OR5B21 (olfactory receptor family 5 subfamily B member 21)
Description:
Odorant receptor.
Tractability: Antibody: UniProt places it where antibodies can reach, with high confidence; UniProt predicts a signal peptide or a membrane-spanning region; its Gene Ontology location is reachable by antibodies, with medium confidence.
Gene: Protein-coding gene on chromosome 11 (58,506,807 to 58,508,105, reverse strand). Ensembl gene ENSG00000198283.
Subcellular location: Cell membrane
Pathways (Reactome):
Sensory Perception: Expression and translocation of olfactory receptors
Gene Ontology:
Molecular function: olfactory receptor activity; G protein-coupled receptor activity
Biological process: G protein-coupled receptor signaling pathway; sensory perception of smell; detection of chemical stimulus involved in sensory perception of smell
Cellular component: plasma membrane; membrane
Genetic constraint (gnomAD): Loss-of-function variants: 0 observed, 1 expected, observed/expected ratio (o/e) 0, 90% interval 0 to 1.72. That is too few expected variants to judge how well the gene tolerates losing a copy. Missense variants: 372 observed, 396.01 expected, observed/expected ratio (o/e) 0.94, 90% interval 0.86 to 1.02. Synonymous variants: 151 observed, 151.37 expected, observed/expected ratio (o/e) 1, 90% interval 0.87 to 1.14.
Homologues: Orthologues: macaque OR5B21 (97% identical), chimpanzee OR5B21 (92% identical), rabbit OR5B21 (89% identical), mouse Or5b21 (86% identical), pig OR5B21 (85% identical), rat Or5b21 (85% identical), dog OR5B21 (83% identical), guinea pig OR5B21 (81% identical). Paralogues in human: OR5B12 (71% identical), OR5B3 (68% identical), OR5B2 (67% identical), OR5B17 (63% identical), OR5AR1 (57% identical), OR5AP2 (57% identical), OR8U1 (55% identical), OR5A1 (54% identical), OR9Q2 (54% identical), OR5D18 (54% identical), OR9G4 (54% identical), OR9I1 (54% identical), and 84 more.
Diseases named in the same sentence as OR5B21 in open-access papers:
OR5B21 is named in the same sentence as 2 diseases in open-access papers, as found by Europe PMC text mining. Sharing a sentence is not in itself a finding about the gene and the disease. The quoted sentences say what the papers report.
breast carcinoma (1 paper, 2025). "OR5H2 could regulate endometrial cancer cell proliferation by interacting with the IGF1 signaling pathway, and OR5B21 drove breast cancer metastasis." (PMID 40523880, 2025).
OR5B21 also shares sentences with these, for which no sentence is quoted: endometrial cancer (1 paper).